HSPB8 (heat shock protein family B (small) member 8)
Diseases named in the same sentence as HSPB8 in open-access papers (continued):
Sharing a sentence is not in itself a finding about the gene and the disease.
HSPB8 also shares sentences with these, for which no sentence is quoted: Charcot-Marie-Tooth disease type 2 (3 papers); dilated cardiomyopathy (3); multiple myeloma (3); Alzheimer disease (2); autoimmune disease (2); cardiovascular disease (2); cholangiocarcinoma (2); Ewing sarcoma (2); hematologic malignancies (2); intrahepatic cholangiocarcinoma (2); Ischemic Heart Diseases (2); Parkinson disease (2); tauopathy (2); type II diabetes (2); brain diseases (1); brain edema (1); breast tumor (1); cataract (1); co-infection (1); colon tumor (1); Desmin-Related Cardiomyopathy (1); diabetic cardiomyopathy (1); edema (1); endometrial cancer (1); endometriosis (1); frontotemporal dementia (1); glioma (1); head and neck squamous cell carcinoma (1); Hyperglycemia (1); hypertrophy (1).
A further 18 diseases each share a sentence with HSPB8 in 1 paper.